STAT3 (signal transducer and activator of transcription 3)
Diseases named in the same sentence as STAT3 in open-access papers (continued):
Sharing a sentence is not in itself a finding about the gene and the disease.
periodontitis (continued). "In the present study, we found that the interaction of the transcription factors FOXO1 and STAT3 mediated periodontitis-related lipopeptide FSL-1-induced ITGB6 downregulation in human epithelial cells." (PMID 36299623, 2022). "STAT3 pathway activation is documented in periodontitis and is also found to contribute to neuroinflammation." (PMID 35132337, 2022). "The oral microbiota from periodontitis drive the activation of IL-17+ γδ T cells, and these IL-17+ γδ T cells then promote tumor cell proliferation via the IL-17/STAT3 pathway." (PMID 36000726, 2022). "In the OSCC-with-periodontitis group, both the proportion of IL-17+ γδ T cells and the phosphorylation of STAT3 were higher." (PMID 36000726, 2022). "Furthermore, the STAT3 signaling pathway was markedly activated, playing a crucial role in mediating the intensified neuroinflammation observed in periodontitis model mice subjected to one day of hypobaric hypoxia." (PMID 40799647, 2025). "Similarly, OSCC-with-periodontitis samples showed higher proportions of IL-17 + γδ T cells and STAT3 phosphorylation." (PMID 40924302, 2025). "Furthermore, the combination of periodontitis and hypobaric hypoxia activated the STAT3 signaling pathway, blocking this pathway attenuated the exacerbation of neuroinflammation induced by hypobaric hypoxia in periodontitis mice." (PMID 40799647, 2025). "Moreover, IL-17 administration alleviated osteoblast ferroptosis and promoted osteogenic differentiation via the direct interaction of phosphorylated signal transducer and activator of transcription 3 (STAT3) with NRF2 in periodontitis models." (PMID 40066457, 2025). "A periodontitis model was established in mice with conditional deletion of Stat3 in Th17 cells (Stat3fl/fl; Il17a-CreERT2, cKO) and wild type (Stat3fl/fl, WT) mice via injection of Porphyromonas gingivalis lipopolysaccharide (P. gingivalis LPS) into gingival sulcus." (PMID 40933993, 2025). "Furthermore, we established an experimental periodontitis model in mice with the conditional knockout of Stat3 in Th17 cells to evaluate the effects of Th17 pathogenicity on cognitive function." (PMID 40933993, 2025). "Additionally, STAT3 phosphorylation was activated in OSCC with periodontitis but declined upon γδ T cell inhibition, suggesting a pivotal role of γδ T cells in tumor progression via IL-17A and STAT3 signaling." (PMID 40924302, 2025). "Similarly, through the Stat3 pathway and interleukin-17-positive (IL-17+) γδ T-cells axis, the oral microbiota found in periodontitis, particularly with a dominant presence of Porphyromonas, has been implicated in the promotion of oral SCC." (PMID 39315107, 2024). "It has been reported that USP5 is upregulated in the gingival crevicular fluid and gingival tissues of patients with periodontitis, showing a positive correlation with proinflammatory factors through the STAT3 signaling pathway, which exacerbates the inflammatory response in chronic periodontitis." (PMID 38322269, 2024). "However, the treatment with C188-9, a synthetic small molecule that specifically inhibits the STAT3 pathway, showed obvious suppression of this pathway in BM-MSCs from periodontitis mice." (PMID 37490712, 2023). "It was reported that TLR4 activated the NF-κB signaling pathway to induce the release of pro-inflammatory factors, and Resveratrol played protective effects against experimental periodontitis in mice via inhibiting the phosphorylation of NF-κB signaling molecules, including p65, p38MAPK, and STAT3." (PMID 38007427, 2023).
periodontitis (continued). "Our results indicate that the JAK/STAT3 pathway is involved in the immunoregulation of BM-MSCs, and provide critical insight into the development of novel targeted therapies against periodontitis and perhaps also other inflammation/immune disorder-related diseases." (PMID 37490712, 2023). "However, the role of the IL-17/STAT3 pathway in promoting tumorigenesis upon activation by the oral microbiota from periodontitis is still unappreciated." (PMID 36000726, 2022). "γδ T cells regulate the IL-17/STAT3 pathway in OSCC with periodontitis." (PMID 36000726, 2022). "Furthermore, the reciprocal action of STAT3 and FOXO1 on ITGB6 downregulation was also confirmed by the immunostaining of the inflammatory epithelium associated with periodontitis." (PMID 36299623, 2022). "In summary, we found that hypobaric hypoxia exposure aggravated systemic inflammation and even promoted neuroinflammation in ligature-induced periodontitis mice, and the STAT3 signaling pathway may play an important role in inducing and amplifying neuroinflammation." (PMID 40799647, 2025). "Periodontitis-associated changes in gene expressions, including downregulated expressions of LncRNA SPIRE1 or PRLR, and increased miR-181a-5p expression, resulted in significantly activated JAK/STAT3 signaling in normal BM-MSCs, in comparison to the transfected control cells." (PMID 37490712, 2023). "However, it is still unclear whether STAT3 plays a role in FSL-1-induced cellular effects in periodontitis." (PMID 36299623, 2022). "Therefore, the interaction of FOXO1 and STAT3 may contribute to periodontitis progression by inhibiting ITGB6 expression." (PMID 36299623, 2022). "Using a newly-established murine oral tumorigenesis model that is associated with periodontitis, it was reported that chronic bacterial infection supports development of OSCC, inducing enhanced signaling of the IL-6- signal transducer and activator of transcription 3 (STAT3) pathway." (PMID 30837987, 2019). "These in vivo results suggest that TEPP-46’s therapeutic effect on periodontitis comes from inhibiting PKM2 nuclear translocation, thereby reducing STAT3 phosphorylation and subsequently reducing osteoclastogenesis." (PMID 40057191, 2025). "Both IL6/JAK/STAT3 and TGF-β1/SMAD pathways play crucial roles in the inflammatory and fibrotic responses in periodontitis and renal pathology." (PMID 40452929, 2025). "In contrast, 8 MRs (ESR1, CEBPB, FOS, BCL6, E2F1, SPI1, STAT3, and ETS1) were consistently expressed at higher levels (U test statistic between 10 and 16) in the periodontitis condition." (PMID 37834287, 2023). "Our data demonstrated that, with the expansion of IL-17+ γδ T cells and increased expression of IL-17A, the STAT3 phosphorylation was also activated in both the early stage and late stage of OSCC with periodontitis." (PMID 36000726, 2022). "In summary, we developed a Lipo-RSV system to treat periodontitis by modulating p-STAT1 and p-STAT3 to reprogram the macrophages from M1- to M2-like phenotype." (PMID 34930286, 2021). "Therefore, IL-6 and TGF-β1 were selected due to their direct involvement in the specific pathways such as IL6/JAK/STAT3 and TGF-β1/SMAD linking periodontitis and renal pathology." (PMID 40452929, 2025). "We further established a periodontitis model through injection of P. gingivalis LPS in mice with conditional deletion of Stat3 in their Th17 cells (Data of gene knockout validation not shown)." (PMID 40933993, 2025). "In addition, mandibular BM-MSCs from periodontitis mice also showed markedly more activated JAK/STAT3 signaling, as evidenced by higher levels of JAK2 and phosphorylated STAT3 proteins." (PMID 37490712, 2023). "Moreover, the proportion of IL-17+ γδ T cells and the phosphorylation of STAT3 were higher in the tissues obtained from OSCC patients with periodontitis group compared to OSCC patients without periodontitis." (PMID 37373022, 2023).
periodontitis (continued). "To confirm the role of FOXO1 and STAT3 and its relation to ITGB6 expression in vivo, we performed immunohistochemistry to detect the expression of ITGB6, FOXO1, and STAT3 using sequencing slices from healthy human gingival tissue and gingival epithelium of patients with periodontitis." (PMID 36299623, 2022).
atopic dermatitis (40 papers, 2017 to 2026). "Experimental models of atopic dermatitis and rosacea have shown that both overactivation and deficiency of STAT3 can aggravate barrier dysfunction and inflammation, underscoring STAT3-centered pathways as a critical mechanistic axis." (PMID 41373824, 2025). "The most common manifestation is atopic dermatitis, seen in all reported cases, as in STAT3 deficiency." (PMID 39459629, 2024). "Most of these applications showed effectiveness against skin-associated diseases, such as ItP of IL-10 for atopic dermatitis, STAT3 siRNA for skin cancer, and TNF-α drug etanercept for psoriasis." (PMID 38140019, 2023). "Defects in filaggrin and STAT3 are associated with atopic dermatitis (AD) and susceptibility to severe skin infection." (PMID 28081250, 2017). "Although earlier studies have suggested a role for HDAC6 in modulating STAT3 acetylation in allergic dermatitis, the direct relationship between HDACs and FLG expression has remained unclear." (PMID 40730500, 2025). "There is little mechanistic understanding of the pathogenesis of atopic dermatitis (AD) in STAT3 GOF and JAK1 GOF." (PMID 37140667, 2023). "Since atopic dermatitis can also occur in STAT3 GOF patients, the relationship of the two disease entities in terms of this complication needs to be discussed." (PMID 37140667, 2023). "The mTOR and STAT3 signaling pathways have been known as crucial for maintaining homeostasis of skin barrier in pathophysiology of atopic dermatitis." (PMID 34946332, 2021). "It is known that both IL-31 and IL-33 initiate skin inflammation and lead to the dysregulation of immunomodulatory proteins in atopic dermatitis through STAT3 pathway activation." (PMID 32566105, 2020). "Oclacitinib, an FDA-approved JAK inhibitor for the treatment of atopic dermatitis in dogs, blocks IL-6 signaling and subsequent STAT3 phosphorylation at recommended dosing, thus represents a viable approach to targeting STAT3 in veterinary cancer patients." (PMID 31409327, 2019). "Activation of STAT3 is important for the development of atopic dermatitis, thus, several anti-inflammatory compounds such as quercetin that can inhibit the development of atopic dermatitis by preventing STAT3 activation." (PMID 30430364, 2019). "aureus isolates from patients with AD-HIES, and three of the nine S. aureus isolates from STAT3-sufficient patients with atopic dermatitis (3/9)." (PMID 28587312, 2017). "STAT3 LOF mutations have been observed to be closely associated with a reduced proportion of Th17 cells (less than 0.3% of CD4+ T cells), in contrast to atopic dermatitis patients with unaffected STAT3 who generally exhibit significantly elevated levels of Th17 cells." (PMID 40040707, 2025). "Elimination of STAT3 inhibits the polarization of human monocyte-derived macrophages to the M2 phenotype, whereas activation of STAT3 promotes the M2 polarization of macrophages in atopic dermatitis and PF mouse models." (PMID 40092491, 2025). "The only available study on skin microbiome dysbiosis in humans to date included patients that did not have the severe eczematous phenotype, with significantly lower SCORAD (Scoring Atopic Dermatitis) scores and with lower IgE levels than included patients with AD, STAT3-HIES, and DIDS." (PMID 41181176, 2025). "Furthermore, TEO likely alleviates inflammation by suppressing the TLR2/STAT3 signaling pathway, as evidenced by the anti-inflammatory effects of Cupressaceae terpenoids in atopic dermatitis models." (PMID 41471858, 2025). "Regarding the risk of allergic disease, patients with STAT3-HIES, despite elevated IgE levels, experience lower rates of allergy and anaphylaxis compared to individuals with similar IgE levels and atopic dermatitis, although these rates are still higher than in the general population." (PMID 39459629, 2024).
atopic dermatitis (continued). "Since most patients with atopic dermatitis develop the disease in early childhood and show symptom relief as they grow up, STAT3 signaling may play a particularly important role as a defense against bacteria in the immature skin immune environment of early childhood." (PMID 34867936, 2021). "Isoliquiritin downregulates the JAK/STAT signaling pathway by inhibiting the phosphorylation of JAK2, STAT1, STAT3, and STAT5, thereby regulating immune and inflammation responses and contributing to the treatment of atopic dermatitis." (PMID 40657637, 2025). "It is known that in keratinocytes of atopic dermatitis, IL-4 activates STAT3 to promote the transcription of TSLP, which in turn inhibits the expression of filaggrin by upregulating the STAT3/ERK pathway." (PMID 39684369, 2024). "Based on the suppressor of cytokine signaling 1 (SOCS1)/Janus kinase (JAK)/signal transducer and activator of transcription 3 (STAT3) pathway, the mechanism of oxymatrine in the treatment of atopic dermatitis (AD) was preliminarily explored in this study." (PMID 36703757, 2022). "Thus, compounds inhibiting STAT3 could be effective for atopic dermatitis." (PMID 30430364, 2019).
chronic myeloid leukemia (40 papers, 2009 to 2025). "Doxorubicin-resistant chronic myeloid leukemia cells enhanced phosphorylation of STAT3 and dampened the tumor growth inhibition of TNF-α." (PMID 32872659, 2020). "A recent study identified FOXM1 as a new STAT3 gene target and clarified its role in proliferation, survival, drug resistance, and DNA repair in chronic myeloid leukemia." (PMID 30782607, 2019). "Resistance to imatinib in chronic myeloid leukemia is conferred by the activation of STAT3 signaling, and the sensitivity is restored by STAT3 inactivation." (PMID 26547689, 2015). "In this study, we characterized STATIP1 in the K562 cell line and investigated its role in STAT3 transcriptional activity in a distinct cell line established from another cancer type, chronic myeloid leukemia." (PMID 25417721, 2014). "Constitutive activation of STAT5 is known to be critical for the maintenance of chronic myeloid leukemia and STAT3 is also constitutively active in Bcr-Abl-positive embryonic stem cells." (PMID 24155950, 2013). "Our study provides the identification of FoxM1 as a new STAT3 gene target and clarifies its role in proliferation, survival, drug resistance and DNA repair in chronic myeloid leukemia." (PMID 23110199, 2012). "Examples include a study on chronic myeloid leukemia stem cells, which showed that HH-dependent Stat3 activation orchestrates down-regulation of Hox genes such as HoxA2 and HoxB4." (PMID 19575820, 2009). "STAT3 dephosphorylation can sensitize doxorubicin-resistant Dalton lymphoma to dendritic cell (DC)-derived TNF-α through the downregulation of Bcl-2 upon cucurbitacin I (STAT3 inhibitor) treatment in DC (chronic myeloid leukemia) patients." (PMID 32872659, 2020). "Intriguingly, the ability of Hh to crosstalk with Wnt is suggested by Sengupta and coworkers, who demonstrated that Hh signaling via Stat3 activation gives rise to the expression of Wnt3a, Lef1, Gli1–3, and other target genes in the chronic phase of chronic myeloid leukemia (CML)." (PMID 31552081, 2019). "Increased expression of Stat3 and C/ebpβ is found in chronic myeloid leukemia (CML)." (PMID 29382715, 2018). "Among these genes, MTOR, STAT3, MCL1, LAMC1, and KRAS have been reported to play roles in imatinib resistance in chronic myeloid leukemia in parallel with our findings." (PMID 38916832, 2024). "EGCG has been shown to induce apoptosis by targeting JAK2/STAT3/AKT and Bcr/Abl-mediated p38-MAPK/JNK signalling pathways in chronic myeloid leukaemia (CML) cells." (PMID 33802972, 2021). "Chronic myeloid leukemia (CML) is driven by the BCR-ABL fusion oncoprotein, which is involved, among other pathways, in the transcriptional regulation of STAT3 and STAT5." (PMID 31861612, 2019). "In hematological malignancy, Icaritin strongly inhibits growth of primary chronic myeloid leukemia (CML) cells in vitro and in vivo by regulating the MAPK/ERK/JNK and JAK2/STAT3/AKT pathways." (PMID 25887673, 2015). "Flavopiridol in combination with bortezomib also inhibits activity of STAT3 and STAT5 and induces apoptosis in chronic myeloid leukemia." (PMID 24199193, 2013). "Tandem affinity purification (TAP)-tagged monobodies were stably expressed in two cell lines that endogenously express STAT3 and various other STAT family members at different levels: K562 chronic myeloid leukemia cells and Jurkat acute lymphoblastic leukemia T-cells." (PMID 32807795, 2020). "Moreover, in chronic myeloid leukemia blast cells, the long noncoding RNA MEG3 interacted with multiple proteins in a large complex comprising DNMT1, JAK2, TYK2, STAT3, and HDAC155." (PMID 32895373, 2020). "Combined inhibition of STAT3 and STAT5 by shRNAs also suppressed growth in chronic myeloid leukemia, suggesting that combinatorial suppression of STAT3 and STAT5 may be efficacious in treating hematological malignancies." (PMID 31684144, 2019).